RNU6-807P (RNA, U6 small nuclear 807, pseudogene)
Gene: Small nuclear RNA gene on chromosome 15 (101,648,206 to 101,648,312, reverse strand). Ensembl gene ENSG00000252614.
Homologues: Orthologues: chimpanzee U6 (98% identical), macaque U6 (90% identical), guinea pig U6 (69% identical), pig U6 (69% identical), dog U6 (68% identical), mouse Gm24468 (66% identical), rabbit U6 (66% identical), rat LOC120103217 (64% identical). Paralogues in human: RNU6-653P (79% identical), RNU6-1056P (77% identical), RNU6-1123P (77% identical), RNU6-1329P (77% identical), RNU6-1020P (76% identical), RNU6-1029P (76% identical), RNU6-275P (76% identical), RNU6-296P (76% identical), RNU6-379P (76% identical), RNU6-43P (76% identical), RNU6-454P (76% identical), RNU6-1094P (75% identical), and 1285 more.